BRAF (B-Raf proto-oncogene, serine/threonine kinase)
Diseases named in the same sentence as BRAF in open-access papers (continued):
Sharing a sentence is not in itself a finding about the gene and the disease.
tumor (continued). "Since immunotherapy can be proposed alone or in combination with first-line chemotherapy in patients whose tumors are wild type for EGFR, ALK, ROS1, and BRAF, it is obligatory to obtain the PD-L1 status of tumor cells." (PMID 32294880, 2020). "Among cases with respective tumor marker data, 19.8% were MSI-H (n = 719), 24.3% were CIMP-positive (n = 841), 18.4% were BRAF-mutated (n = 654), and 32.0% were KRAS-mutated (n = 1098)." (PMID 32923935, 2020). "Preclinical studies demonstrated that PD-1/PD-L1 blockade was effective in reducing tumor growth and, when anti-PD-1/PD-L1 antibody was administered in combination with a BRAF-inhibitor, it reduced tumor volume and prolonged survival in murine models." (PMID 33292371, 2020). "The primary tissue samples (FFPE tumor tissue) of all patients were classified as RAS-mutated and BRAF wild-type by next generation sequencing according to routine molecular-pathologic techniques." (PMID 32766143, 2020). "The factors associate with shorter overall survival (OS) in PRODIGE 9 trial were WHO performance status > 2, unresected primary tumor, age over 65 were and BRAF mutant tumor." (PMID 32486421, 2020). "With a cross-sectional design involving an observational analytical approach, we determined the relationship of BRAF V600E and KRAS mutations to the location, histopathology, and degree of tumor differentiation in CRC." (PMID 33145020, 2020). "About OS, in the multivariate analysis of the whole study population, only tumor grade (HR = 5.26, 95% CI 1.98–14.01) and BRAF status (3.71, 95% CI 1.07–12.89) were independent prognostic factors." (PMID 32872561, 2020). "Potential examples of such tumor-agnostic targets other than NTRK include (but not limited to) ALK, BRAF, BRCAness, FGFR, HER2, HER3, homologous recombination deficiency (HRD), KRAS, RET, ROS1, tumor mutation burden (TMB) high." (PMID 31974683, 2020). "The results suggested an improvement in anti-tumor activity through a triple therapy combination of dabrafenib (BRAF inhibitor), trametinib (MEK inhibitor), and pembrolizumab (anti-PD-1 antibody)." (PMID 32213878, 2020). "Digital PCR-based BRAF genotyping identified BRAFV595E mutation in 33 cUC tissues, while 10 tumours were BRAF wild-type." (PMID 32385388, 2020). "As a result, few prognostic factors have been identified in SIACs such as tumor location (duodenum vs. jejunum and ileum), microsatellite instability (MSI), tumor-infiltrating lymphocytes (TILs), and KRAS or BRAF mutations." (PMID 32781596, 2020). "In our study we demonstrate for the first time that p38 MAPK controls PMCA4b internalization using three different model systems including two tumor cell lines (BRAF mutant A375 and HeLa cells) and the doxycycline inducible non-tumorigenic HEK cell model." (PMID 32414111, 2020). "Targeting specific oncoproteins crucial for tumour growth, such as BRAF, induces adaptive kinome responses that upregulate alternative kinase signalling to overcome the inhibitor treatment." (PMID 32098410, 2020). "The CIMP-(+) tumors of patients with LOCRC presented moderate tumor differentiation (p = 0.045), MSI status (p = 0.021) and a higher BRAF mutation rate (p = 0.001)." (PMID 31324877, 2019). "But it is also possible that the mutations are due to tumor heterogeneity resulting in the selection and outgrowth of multiple‐resistant RAS/BRAF‐mutated subclones, which are below the limit of detection at baseline." (PMID 31350822, 2019). "The NRF1-BRAF fusion in our patient's tumor contains exon 1–10 of the NRF1 gene and retains the entire kinase domain of the BRAF gene." (PMID 31010895, 2019). "Both of these studies suggest utility of testing ctDNA BRAF levels in patients receiving combination therapy of anti-EGFR and BRAF inhibitor to monitor tumor response." (PMID 31824558, 2019).
tumor (continued). "Applying a targeted next generation sequencing panel the tumor demonstrated an activating TERT promoter mutation, a HRAS G12S mutation as well as a BRAF G466E mutation." (PMID 30809375, 2019). "Patients with gene mutations in the tumor had a shorter survival time than patients with the wild type gene, except for NRAS, BRAF, and EGFR mutations." (PMID 31255173, 2019). "Inhibitors of porcupine have demonstrated promising results in phase I clinical trials, inducing tumor regression in BRAF-mutant CRC, TNBC and pancreatic cancer patients." (PMID 31412666, 2019). "We found 9 (15.2%) CIMP-(+) EOCRC patients related with the proximal colon (p = 0.008), and 19 (26.8%) CIMP-(+) LOCRC patients associated with tumor differentiation (p = 0.045), MSI status (p = 0.021) and BRAF mutation (p = 0.001)." (PMID 31324877, 2019). "Unfortunately, although BRAF/MEK combo-therapy leads to a more durable control of tumor growth and to prolonged survival, it is unable to completely eradicate disease." (PMID 30254376, 2019). "We highlight common mechanistic themes that underpin different classes of resistance mechanisms against BRAF-targeted therapies and discuss tumor heterogeneity and co-occurring molecular alterations as a potential source of therapy resistance." (PMID 31426419, 2019). "By contrast, for oncogenes (orange) with variants highly concentrated at hotspots, particularly KRAS, BRAF, IDH1, the probability of encountering new variants in future tumor samples tends to be low." (PMID 31796730, 2019). "Using tumors cells and human-derived murine xenografts, we show that tumor sweep dynamics can significantly affect responses to targeted inhibitors of BRAF/MEK or DNA damaging agents." (PMID 31723142, 2019). "Fourteen CNS-JXG cases (64%) had informative molecular status for the BRAF V600E point mutation, which included 10 pediatric CNS-JXG neoplasms that were included in the primary analysis." (PMID 31685033, 2019). "BRAF V600E and SRC mutations were mutually exclusive, and SRC mutation was significantly associated with left-sided tumor and liver metastasis compared to BRAF V600E mutation (P = 0.016 and P = 0.025, respectively)." (PMID 30792536, 2019). "By far, the most frequent mutation in BRAF across all cancer types is BRAFV600E, which drives tumor growth by hyperactivating the mitogen-activated protein kinase (MAPK) signaling pathway." (PMID 31723142, 2019). "Epigenetic plasticity, often modulated by histone-modifying enzymes and gene regulation, can influence a tumor cell’s BRAF dependency and therefore, response to therapy." (PMID 31581557, 2019). "When patients undergoing metastasectomy were excluded, BRAF- and RAS-mutated tumours had a shorter PFS and OS than wild-type tumours." (PMID 30585257, 2019). "This sits well with the evidence that BRAF inhibition can improve the efficacy of PD-1 blockade via changes in the tumor microenvironment." (PMID 31921863, 2019). "Sixteen of 25 plasma samples had detectable level of KRAS (n = 14), BRAF (n = 1) or NRAS (n = 1) mutations, which were 100% concordant to reported tumour DNA genotype." (PMID 30585255, 2019). "All tumors were analyzed using an NGS multi-gene panel that expands the tumor genetic portrait, including genes such as BRAF, ERBB2, KRAS, and MET in addition to EGFR and ALK/ROS1, in accordance with recently updated recommendations." (PMID 30669267, 2019). "In another report, the additional administration of vemurafenib to an adoptive transfer of autologous TILs significantly enhanced the anti-tumor effects of patients’ TILs in BRAF-resistant tumor-bearing xenograft mice." (PMID 31514399, 2019). "The initial mutational status (i.e., mutations in BRAF, NRAS) of the primary tumor was recovered in CTC and ctDNA in 47.6–70.6% of all cases." (PMID 31671846, 2019).
tumor (continued). "Despite limitations imposed by the blood–brain barrier and adaptive tumor resistance to the growth-inhibitory effects, the possible application of BRAF targeted therapy in CNS tumors grows continuously." (PMID 31181803, 2019). "There are data that BRAF V600E tumors that respond to targeted therapies and later progress can de-differentiate on progression, so it is interesting that the tumor transformed to a high grade after vemurafenib treatment." (PMID 31158244, 2019). "A further biological effect of BRAF inhibitors is related to their anti-cancer activity in the tumor microenvironment milieu, which, by improving the anti-tumor activity of the patient’s immune system, limits cancer progression." (PMID 31762942, 2019). "CIN occurs more frequently in tumour showing APC and KRAS mutations, whereas the microsatellite instability phenotype is mainly associated with BRAF mutations." (PMID 31414579, 2019). "An even greater anti-tumor effect was observed when treatment with BRAF-inhibitors was combined with: i) anti PD-L1 or anti PD-1 antibodies; ii) the BCR/ABL tyrosin-kynase inhibitor Dasatinib; iii) proteasome inhibitors like Bortezomib." (PMID 31762942, 2019). "Tumor that origins from the two sites of the colon has different molecular carcinogenic characters, including KRAS, BRAF mutations and microsatellite instability (MSI)." (PMID 30917791, 2019). "The combination of RAF and MEK inhibitors produces more durable inhibition of ERK signaling and more potent effects on tumor growth inhibition in models of BRAF V600E." (PMID 31158244, 2019). "In BRAFV600E cells, KIT suppresses the RAS/MAPK pathway activity mediated by BRAF activation, and acts as a tumor suppressor." (PMID 31426590, 2019). "We also found that BRAF normalized read counts were higher in cancer cells expressing the MAPK gene programme (tumor cluster 0) compared to those expressing the AC-like gene programme (tumor cluster 1) (P = 0.003 using Fisher’s method)." (PMID 31427603, 2019). "Several in vitro studies aimed at evaluating the effect of different BRAF-inhibitors on immune-infiltrating cells (T cells, lymphocytes, dendritic cell) of tumor microenvironment were performed." (PMID 31762942, 2019). "They found an enrichment of tumours with HER2 amplification in cetuximab‐resistant KRAS/NRAS/BRAF/PIK3CA wild‐type tumours." (PMID 31282586, 2019). "Within the 2011–2012 cohort, patients within the OEG were predominantly older (median age: 62), female (67%), possessed right sided tumours (89%), with deficient MLH1 (56%) expression, of which 60% harboured BRAF mutations." (PMID 31636305, 2019). "Our results further emphasize the importance of BRAF alterations in PA and the need to characterize them in a given tumor as this can affect therapeutic strategies and their potential use as tumor marker in molecular diagnostics." (PMID 30575814, 2019). "Translational studies also support the anti-cancer effect of BRAF inhibitors resulting from changes in the immunophenotype of tumor microenvironment." (PMID 31762942, 2019). "Unfortunately, despite pronounced reduction in tumour burden and significant increases in patient survival, most responses to BRAF inhibitors remain transient, as a result of primary or acquired resistance." (PMID 31416288, 2019). "Several studies have incorporated CMS with other molecular features to in order to refine prognostic groups, and have described poorer outcomes in BRAF-mutated CMS1 MSS tumours, and KRAS-mutated CMS2/3 MSS tumours, and favourable outcomes in CMS1 MSI tumours." (PMID 31775679, 2019). "Genetic analysis of tumor tissue was performed using a diagnostic biochip (EIMB RAS, Russia) for the detection of most common somatic mutations in the BRAF, NRAS, KIT, GNAQ, GNA11, MAP2K1, and MAP2K2 genes." (PMID 30782194, 2019).
tumor (continued). "The uncommon occurrance of mutant BRAF together with the generally higher rate of multifocality would argue against a carcinogenetic role of mutant BRAF in early tumor formation induced by HT." (PMID 30666518, 2019). "Compared with these biomarkers, all the seven prognostic CpGs were selected through multivariable Cox regression with adjustment considering tumor stage, MSI status, and BRAF mutation status as confounders." (PMID 31340858, 2019). "Studies on American CRC populations have indicated that CIMP is significantly associated with female sex, older age, proximal tumour location, MSI, BRAF mutation, and wild-type KRAS." (PMID 31690257, 2019). "In tumor tissue, KRAS or BRAF mutations were present in 35 of 65 cases (44% UICC stage I, 50% stage II, 47% stage III, and 62% stage IV)." (PMID 31134762, 2019). "In order to identify possible mechanisms of resistance to anti-EGFR MoAbs in CRC, we analyzed tumor samples from 21 KRAS/NRAS/BRAF/PIK3CA wt mCRC patients enrolled in the CAPRI-GOIM clinical trial by targeted sequencing." (PMID 31226844, 2019). "Abrogating TAFs which was mediated by IL-1 in the stroma is another mechanism of suppression of immunosuppressive tumor microenvironment with BRAF inhibition." (PMID 31134073, 2019). "In the case of dMMR/MSI CRC with MLH1 loss and BRAF wild type status, MLH1 promoter methylation is determined and a MLH1 promoter hypermethylation signs the sporadic trait of the tumor." (PMID 31618962, 2019). "In subgroup analyses stratified by tumor location, MSI status, and BRAF mutation status, similar results were observed for the association between the prognostic scores and DSS." (PMID 31340858, 2019). "The model was adjusted for tumor stage, sex, MSI, the genomic fraction of AI, BRAF mutation and CIMP status." (PMID 31492840, 2019). "We also tested the thyroid specimen for BRAF V600E mutation by polymerase chain reaction (PCR), and it was found to be positive in both the PTC and SMECE tumors of the thyroid." (PMID 31882020, 2019). "Correlation analysis using available clinicopathological information revealed that PIK3CA H1047R and BRAF V600E MFs correlate positively with maximum tumor dimension." (PMID 30813596, 2019). "Although they display hypermethylation events that commonly characterize all BRAF mutant cancers, this subset of tumor shows lower frequency of CIMP than BRAF/MSI cancers." (PMID 31455041, 2019). "There remains an open question as to how to best identify intra- and inter-tumor heterogeneity of BRAF-mutant cancers and how to best account for it in order to strategize improved treatment options." (PMID 31426419, 2019). "Evidence that BRAF inhibitors do play a role in determining the specific composition of the tumor microenvironment was also provided by translational studies." (PMID 31762942, 2019). "Similar antitumor response has been observed with the combination of BRAF inhibition and PD-1 pathway blockade through increasing number and function of tumor-infiltrating T cells." (PMID 31134073, 2019). "Histopathological features were further stratified by ethnic groups (black versus OEG) to assess if any associations occurred with regard to gender, age, tumour site, MMR protein expression profile and BRAF mutation status." (PMID 31636305, 2019). "We specifically focused on currently available factors associated with thyroid carcinogenesis, including histology, tumor multifocality and further, the prominent performers of the MAP kinase pathway, BRAF and NRAS mutational status." (PMID 30666518, 2019). "BRAF mutant causes continuous activation of MAPK pathway and leads to uncontrolled proliferation of tumor cells with multiple mechanisms, making itself an attractive therapeutic target." (PMID 31134073, 2019).
tumor (continued). "MSI/BRAF wild-type tumours are also more suggestive of LS and is crucial for improving cancer surveillance and prevention screening for patient family members, due to their increased risk of developing cancer." (PMID 31636305, 2019). "For example, adaptive overexpression of stromal HGF secretion and underexpression of CTLA4, BIM, and antigen presentation genes (B2M, HLA-A, HLA-B, and TAP1) have been cited as mechanisms of tumor resistance upon BRAF inactivation." (PMID 31426419, 2019). "In an own study, we employed single-cell RNA-seq to individually profile several hundreds of tumor cells taken from biopsies of three patients with different genetic backgrounds regarding BRAF and NRAS." (PMID 30987166, 2019). "Five (10.4%) and 31 (64.6%) patients presented BRAF mutations and KRAS mutations in at least one tumor, respectively." (PMID 31324877, 2019). "In RAS/BRAF wild-type tumours, the median PFS and OS were 9.8 versus 8.6 months and 29 versus 17 months, respectively." (PMID 30585257, 2019). "The case encourages discussion about the most appropriate adjuvant therapy for tumor progression in such cases, given the risks of radiotherapy to the developing brain and the increasing availability of oral BRAF inhibitor therapy." (PMID 30069716, 2019). "Recently, markers of tumour biology and genetics such as the RAS or BRAF mutational status are more commonly included in clinical risk scores and algorithms for oncosurgical treatment." (PMID 31150437, 2019). "In patients with BRAF mutations, dabrafenib plus trametinib can also be alternatively recommended for stage III disease with ≥1 mm tumor burden in the SLN." (PMID 31696119, 2019). "We next examined the original tumor and MBC02 cell line for the presence of common mutations in KRAS (codons 12, 13, 61, and 146) and BRAF (V600E) that are prevalent among CRC patients." (PMID 30828563, 2019). "We demonstrate that such trajectories are associated with a collapse of genetic diversity and a strong propensity for a dominant subclone, resulting in a greater threat to tumor extinction (i.e., better response to BRAF-pathway inhibition)." (PMID 31723142, 2019). "The presence of a PTEN mutation was significantly associated with a right-sided tumor, mucinous histology, high MSI status, BRAF mutation, and high CIMP status." (PMID 31717544, 2019). "A promise of precision oncology is that the genomic-scale understanding of BRAF-mutant tumors, both at baseline and longitudinally during treatment, will allow for predicting tumor evolutionary trajectories at a higher resolution." (PMID 31426419, 2019). "Studies from the U.S. have shown that BRAF variant V595E (cBRAF reference sequence ENSCAFT00000006306), which corresponds to the BRAF (V600E) variant in humans, can be found in tumor cells of 65–85% of dogs with TCC." (PMID 30893857, 2019). "One patient was positive for BRAF p.V600E in the primary tumour, but positive for p.V600D in the metastasis." (PMID 31767937, 2019). "It will be interesting to determine the contribution of truncated PPM1D to tumor development using the BRAF-V600E mouse model." (PMID 31659152, 2019). "In the CheckMate 142 trial, nivolumab, a checkpoint inhibitor targeting PD1, was tested in 74 pre-treated MSI mCRC patients, 12 (16%) of whom had BRAF-mt tumours." (PMID 31353365, 2019). "In fact, an increasing number of studies suggest that hyperactivation of the PI3K/AKT signaling pathway is as important as the BRAF-MEK-ERK pathway during tumor development and progression." (PMID 31183073, 2019). "Alterations of the v-raf murine sarcoma viral oncogene homolog B (BRAF) have been extensively studied in several tumor entities and are known to drive cell growth in several tumor entities." (PMID 31181803, 2019).